ATP5F1B (ATP synthase F1 subunit beta)
Description:
Catalytic subunit beta, of the mitochondrial membrane ATP synthase complex (F(1)F(0) ATP synthase or Complex V) that produces ATP from ADP in the presence of a proton gradient across the membrane which is generated by electron transport complexes of the respiratory chain (Probable). ATP synthase complex consist of a soluble F(1) head domain - the catalytic core - and a membrane F(1) domain - the membrane proton channel. These two domains are linked by a central stalk rotating inside the F(1) region and a stationary peripheral stalk. During catalysis, ATP synthesis in the catalytic domain of F(1) is coupled via a rotary mechanism of the central stalk subunits to proton translocation (Probable). In vivo, can only synthesize ATP although its ATP hydrolase activity can be activated artificially in vitro (By similarity). With the subunit alpha (ATP5F1A), forms the catalytic core in the F(1) domain.
Synonyms: ATP5B; ATPMB; ATPSB; DYT38; HEL-S-271; HUMOP2
Tractability: Small molecule: a structure with a bound ligand is known. Antibody: its Gene Ontology location is reachable by antibodies, with high confidence; UniProt places it where antibodies can reach, with medium confidence. PROTAC: ubiquitination databases record sites on it.
Target class: Enzyme; Hydrolase
Chemical probes: APOPTOLIDIN (high quality), Ammocidin-A
Gene: Protein-coding gene on chromosome 12 (56,638,171 to 56,646,079, reverse strand). Ensembl gene ENSG00000110955.
Subcellular location: Mitochondrion inner membrane
Subcellular location (Human Protein Atlas): Mitochondria
Pathways (Reactome):
Organelle biogenesis and maintenance: Cristae formation; Transcriptional activation of mitochondrial biogenesis
Metabolism: Formation of ATP by chemiosmotic coupling
Metabolism of proteins: Mitochondrial protein degradation
Protein localization: Mitochondrial protein import
Gene Ontology:
Molecular function: angiostatin binding; MHC class I protein binding; protein binding; proton-transporting ATP synthase activity, rotational mechanism; proton-transporting ATPase activity, rotational mechanism; ATP binding
Biological process: angiogenesis; ATP biosynthetic process; osteoblast differentiation; positive regulation of blood vessel endothelial cell migration; proton motive force-driven ATP synthesis; proton motive force-driven mitochondrial ATP synthesis; proton transmembrane transport; regulation of intracellular pH; generation of precursor metabolites and energy; ATP metabolic process
Cellular component: cell surface; extracellular exosome; membrane; mitochondrial inner membrane; mitochondrial membrane; mitochondrial nucleoid; mitochondrion; nucleus; plasma membrane; proton-transporting ATP synthase complex; mitochondrial matrix; cytoplasm; proton-transporting two-sector ATPase complex; transmembrane transporter complex
Genetic constraint (gnomAD): Loss-of-function variants: 17 observed, 48.01 expected, observed/expected ratio (o/e) 0.35, 90% interval 0.24 to 0.53. The upper end of that interval is the gene's LOEUF score, 0.53, which puts it in group 2 of 6, group 1 being the genes least tolerant of losing a copy. Missense variants: 387 observed, 702.7 expected, observed/expected ratio (o/e) 0.55, 90% interval 0.51 to 0.6. Synonymous variants: 218 observed, 266.8 expected, observed/expected ratio (o/e) 0.82, 90% interval 0.73 to 0.91.
Homologues: Orthologues: chimpanzee ATP5F1B (99% identical), macaque ATP5F1B (99% identical), pig ATP5F1B (97% identical), rabbit ATP5F1B (97% identical), mouse Atp5f1b (96% identical), dog ATP5F1B (96% identical), rat Atp5f1b (96% identical), tropical clawed frog atp5f1b (90% identical), guinea pig ATP5F1B (89% identical), zebrafish atp5f1b (89% identical), Drosophila melanogaster ATPsynbeta (84% identical), Caenorhabditis elegans atp-2 (81% identical). Paralogues in human: ATP6V1B2 (26% identical), ATP6V1B1 (25% identical), ATP5F1A (23% identical), ATP6V1A (23% identical).
Diseases named in the same sentence as ATP5F1B in open-access papers:
ATP5F1B is named in the same sentence as 87 diseases in open-access papers, as found by Europe PMC text mining. Sharing a sentence is not in itself a finding about the gene and the disease. The quoted sentences say what the papers report.
breast carcinoma (10 papers, 2013 to 2025). "Altogether, these results indicate that AURKA, ATP5F1A, and ATP5F1B cooperate in regulating cell cycle progression and in maintaining total ATP levels in breast cancer cells with high AURKA expression." (PMID 37386025, 2023). "Overall, we propose that targeting the AURKA/ATP5F1A/ATP5F1B nexus is a promising avenue to lower breast cancer cell metabolism and reduce cell proliferation." (PMID 37386025, 2023). "After observing that AURKA is at a FRET-compatible distance with ATP5F1A and ATP5F1B, we asked whether these proteins could be a nexus regulating cell cycle progression and ATP levels in breast cancer cells." (PMID 37386025, 2023).
colorectal cancer (5 papers, 2017 to 2025). A primary or metastatic malignant neoplasm that affects the colon or rectum. "Indeed, low levels of ATP5F1B associated with worse prognosis in colorectal cancer treated with 5‐Fluorouracil 41 and resistance to adriamycin in leukemia cells." (PMID 32590878, 2020).
Obesity (5 papers, 2015 to 2025). Accumulation of substantial excess body fat. "ATP5F1B plays a beneficial role in obesity-induced non-alcoholic fatty liver disease (NAFLD) by improving mitochondrial function in hepatic steatosis." (PMID 38703299, 2024). "In addition, an impaired ATP5F1B translation has been correlated with the suppression of muscle metabolism in SKM of individuals with obesity compared to lean subject." (PMID 38703299, 2024). "ATP5F1B abundance was increased in SAT samples from insulin-resistant patients with obesity compared to lean insulin-sensitive controls, demonstrating an important role in the development of obesity-related IR and inflammation due its involvement in energy and free fatty acid metabolism." (PMID 38703299, 2024).
prostate carcinoma (5 papers, 2018 to 2024). A carcinoma that arises from epithelial cells of the prostate gland. "Prostate cancer cell proliferation, migration and invasion were reversed in the SFT2D2‐TBX19 overexpression group following ATP5F1A or ATP5F1B knockdown." (PMID 39540264, 2024).
diabetes (4 papers, 2015 to 2024). "Therefore, while the enhanced functions of ATP5F1B and COX4I2 support cellular metabolism under normal conditions, in the pathological state of diabetes and especially DKA, they might intensify metabolic stress and cellular stress responses." (PMID 39469619, 2024).
glioblastoma (4 papers, 2020 to 2024). The most malignant astrocytic tumor (WHO grade IV). "AURKA is a key factor in the pathogenesis of glioblastoma, and increased levels of ATP5F1A and ATP5F1B were observed in glioblastoma models and are accompanied by an upregulation of oxidative metabolism." (PMID 37386025, 2023).
ovarian carcinoma (4 papers, 2013 to 2022). A malignant neoplasm originating from the surface ovarian epithelium. "The anticancer hormone melatonin upregulated ATP5F1B expression in ovarian cancer." (PMID 32590878, 2020).
gastric cancer (3 papers, 2023 to 2024). A primary or metastatic malignant neoplasm involving the stomach. "As reported, ATP5F1B, a novel RNA-binding protein, is involved in the proliferation and metastasis of gastric cancer cells via the ATP-P2X7-FAK/AKT/MMP2 axis." (PMID 38786611, 2024). "ATP5F1B, an RNA-binding protein, can enhance the proliferative and metastatic capacities of gastric cancer cells through the ATP-P2X7-FAK/AKT/MMP2 pathway." (PMID 38786611, 2024).
COVID-19 (2 papers, 2021 to 2023). A disease caused by infection with severe acute respiratory syndrome coronavirus 2. "Interestingly, we also found that ATP synthesis-related genes (e.g., ATP5F1A, ATP5F1B, ATP5F1C, ATP5F1D, ATP5F1E) were significantly increased in COVID-19 patients." (PMID 37087411, 2023).
Dystonia (2 papers, 2025). An abnormally increased muscular tone that causes fixed abnormal postures. "The two reported monoallelic dystonia‐associated ATP5F1B variants resulted in substitutions of single amino acid residues, and no other predicted LoF alleles in ATP5F1B have been clinically documented as pathogenic until today." (PMID 40276935, 2025). "Like relatives in two published dystonia‐affected families, the mother of P5 carried a disease‐associated ATP5F1B variant but was asymptomatic." (PMID 40276935, 2025). "In this study, we have gathered a set of five patients from four unrelated families with autosomal dominant variants in ATP5F1A or ATP5F1B, further defining the genetic, molecular, and phenotypic profile of ATPase‐related diseases with dystonia and spasticity." (PMID 40276935, 2025). "In addition, our group contributed to the description of two families affected by isolated dystonia who carried candidate variants in the ATPase β‐subunit gene ATP5F1B, but this gene–disease relationship awaits further confirmation." (PMID 40276935, 2025). "Our observations underscore the importance of anticipating a broad phenotypic spectrum for such potential molecular alterations in ATP5F1A/ATP5F1B‐related conditions, ranging from isolated or complex dystonia to HSP and CP." (PMID 40276935, 2025). "No carriers of presumably pathogenic variants in other dystonia candidate genes were detected among our 1924 patients, including the recently proposed genes ATP5F1B, ACBD6, and SPTBN1." (PMID 40533913, 2025). "Screening our data for proposed dystonia candidate genes identified presumably pathogenic variants in CHD6, KCNN2, KLC1, NR4A2, and ZMYND11, but not in others, for example, ATP5F1B, ACBD6, CIZ1, SHQ1, and SPTBN1." (PMID 40533913, 2025).
metastatic disease (2 papers, 2022 to 2024). "This suggests that patients with disomy 3 and low ATP5F1B expression have a reduced risk of metastatic disease vs. patients with disomy 3 and high ATP5F1B." (PMID 36698840, 2022). "Notably, high expression of ATP5F1B in primary UM is significantly associated with reduced progression-free survival and reduced OS, and patients with disomy 3 and low ATP5F1B expression have a reduced risk of metastatic disease." (PMID 38341410, 2024). "In UM, high ATP5F1B is a poor prognostic indicator, whereas low ATP5F1B, in combination with disomy 3, correlates with an absence of metastatic disease in the TCGA-UM dataset." (PMID 36698840, 2022).
mesothelioma (1 paper, 2020). A usually malignant and aggressive neoplasm of the mesothelium which is often associated with exposure to asbestos. "Interestingly, ATP5F1b also exists in cell membranes of cancer cells, and potential antibodies targeted to ATP5F1b resulted in better survival in mesothelioma." (PMID 32590878, 2020).
morbid obesity (1 paper, 2024). An excess of body weight, normally defined as an individual with a body mass index greater than 35 or a body weight greater than one hundred percent of ideal body weight. "In accordance with this result, ATP5F1B was also increased on SAT from individuals with morbid obesity compared to lean subjects, supporting those metabolic differences in both groups." (PMID 38703299, 2024).
triple-negative breast carcinoma (1 paper, 2023). An invasive breast carcinoma which is negative for expression of estrogen receptor (ER), progesterone receptor (PR), and human epidermal growth factor receptor 2 (HER2). "Last, we discover that the roles of the AURKA/ATP5F1A/ATP5F1B nexus depend on the specific metabolic propensity of triple-negative breast cancer cell lines, where they correlate with cell fate." (PMID 37386025, 2023). "Altogether, these data further support the direct role of AURKA, ATP5F1A, and ATP5F1B within a potential metabolic nexus in triple-negative breast cancer cells." (PMID 37386025, 2023).
tumor (29 papers, 2009 to 2025). "At the metabolic level, key proteins in the oxidative phosphorylation pathway-such as ATP5F1B, NDUFA9, and UQCRC2—were consistently downregulated across all tumor samples, covering multiple core subunits of the mitochondrial respiratory chain complexes." (PMID 41480141, 2025). "OXPHOS-related proteins (e.g., ATP5F1B, NDUFA9, UQCRC2) were broadly downregulated in tumor tissues, spanning multiple core subunits of the five complexes of the mitochondrial electron transport chain, suggesting impaired mitochondrial energy production." (PMID 41480141, 2025).
cancer (21 papers, 2012 to 2025). A tumor composed of atypical neoplastic, often pleomorphic cells that invade other tissues. "For instance, ATP5F1B, encoding a mitochondrial ATP synthase subunit, has been shown to inversely correlate with aerobic glycolysis rates in cancer cells." (PMID 40841456, 2025). "The downregulation of the ATP5F1B is a hallmark of most human cancers and the subsequent decrease in mitochondrial bioenergetics causes a glucose demand in malignancies." (PMID 32590878, 2020). "Our work paves the way to novel anti-cancer therapies targeting the AURKA/ATP5F1A/ATP5F1B nexus to lower cancer cell metabolism and proliferation." (PMID 37386025, 2023). "Last, our data suggest that ATP5F1A and ATP5F1B could be promising targets in AURKA-overexpressing cancers." (PMID 37386025, 2023). "Since AURKA-specific inhibitors show poor efficacy and a high degree of toxicity in clinical trials, the available inhibitors against Complex V functions could be a valuable resource for combinatorial therapies against AURKA and ATP5F1A or ATP5F1B in AURKA-related cancers in the upcoming future." (PMID 37386025, 2023).
infection (7 papers, 2007 to 2024). The state of being infected such as from the introduction of a foreign agent such as serum, vaccine, antigenic substance or organism. "In addition, the interference of human ATP5F1B (HGNC:830) and CCT2 (HGNC:1615) mRNA by siRNA decreases the productive infection of HeLa P4/R5 cells of HIV-1 HXB2." (PMID 36333693, 2022).
movement disorder (1 paper, 2025). Neurological conditions resulting in abnormal voluntary or involuntary movement, which may impact the speed, fluency, quality and ease of movement. "Disease‐related ATP5F1A/ATP5F1B alleles implicated in movement disorders to date were monoallelic missense variants, variably causing compromised ATPase activity and/or reductions in subunit expression levels." (PMID 40276935, 2025). "Overall, this study confirms heterozygous variants in ATP5F1A and ATP5F1B as an underreported cause of a wider range of neurological phenotypes with prominent movement disorders and permits the determination of an expanded mutational spectrum." (PMID 40276935, 2025). "The aim of this study was to redefine the phenotypic and mutational spectrum of movement disorders linked to the ATPase subunit‐encoding genes ATP5F1A and ATP5F1B." (PMID 40276935, 2025).
ATP5F1B also shares sentences with these, for which no sentence is quoted: Parkinson disease (6 papers); Alzheimer disease (3); Huntington disease (3); liver cancer (3); melanoma (3); sleep disorder (3); colon cancer (2); HCMV infection (2); hepatocellular carcinoma (2); hyperlipidemia (2); ischemia (2); neurodegenerative disease (2); neurodevelopmental disorder (2); neurological disease (2); Parkinson’s (2); pituitary adenomas (2); schizophrenia (2); viral infection (2); amyotrophic lateral sclerosis (1); autoimmune disease (1); bacterial infection (1); brain diseases (1); cardiac hypertrophy (1); cervical cancer (1); cervical tumor (1); cholesteatoma (1); chronic lymphocytic leukemia (1); clear cell renal cell carcinoma (1); Cognitive impairment (1); degenerative joint diseases (1).
A further 39 diseases each share a sentence with ATP5F1B in 1 paper.